SP3 (Sp3 transcription factor)
Description:
Transcriptional factor that can act as an activator or repressor depending on isoform and/or post-translational modifications. Binds to GT and GC boxes promoter elements. Competes with SP1 for the GC-box promoters. Weak activator of transcription but can activate a number of genes involved in different processes such as cell-cycle regulation, hormone-induction and house-keeping.
Synonyms: SPR-2; SPR2
Tractability: PROTAC: UniProt records ubiquitination sites on it; ubiquitination databases record sites on it; its protein half-life has been measured.
Gene: Protein-coding gene on chromosome 2 (173,880,850 to 173,965,373, reverse strand). Ensembl gene ENSG00000172845.
Subcellular location: Nucleus; Nucleus, PML body
Subcellular location (Human Protein Atlas): Nucleoplasm; Cytosol
Pathways (Reactome):
Metabolism of proteins: SUMOylation of transcription factors
Gene Ontology:
Molecular function: protein binding; RNA polymerase II transcription regulatory region sequence-specific DNA binding; RNA polymerase II-specific DNA-binding transcription factor binding; sequence-specific double-stranded DNA binding; DNA-binding transcription factor activity, RNA polymerase II-specific; RNA polymerase II cis-regulatory region sequence-specific DNA binding; chromatin binding; cis-regulatory region sequence-specific DNA binding; DNA binding; DNA-binding transcription repressor activity, RNA polymerase II-specific; double-stranded DNA binding; sequence-specific DNA binding
Biological process: negative regulation of DNA-templated transcription; positive regulation of DNA-templated transcription; positive regulation of transcription by RNA polymerase II; regulation of DNA-templated transcription; regulation of transcription by RNA polymerase II; negative regulation of transcription by RNA polymerase II
Cellular component: nucleoplasm; chromatin; nucleus; protein-DNA complex; PML body; transcription repressor complex
Genetic constraint (gnomAD): Loss-of-function variants: 8 observed, 64.04 expected, observed/expected ratio (o/e) 0.12, 90% interval 0.072 to 0.22. The upper end of that interval is the gene's LOEUF score, 0.22, which puts it in group 1 of 6, group 1 being the genes least tolerant of losing a copy. Missense variants: 742 observed, 885.88 expected, observed/expected ratio (o/e) 0.84, 90% interval 0.79 to 0.89. Synonymous variants: 356 observed, 314.69 expected, observed/expected ratio (o/e) 1.13, 90% interval 1.04 to 1.24.
Homologues: Orthologues: chimpanzee SP3 (99% identical), macaque SP3 (99% identical), dog SP3 (98% identical), pig SP3 (98% identical), rat Sp3 (97% identical), mouse Sp3 (97% identical), rabbit SP3 (88% identical), guinea pig SP3 (87% identical), tropical clawed frog sp3 (70% identical), zebrafish sp3a (53% identical), zebrafish sp3b (47% identical). Paralogues in human: SP4 (38% identical), SP1 (37% identical), SP2 (27% identical).
Diseases named in the same sentence as SP3 in open-access papers:
SP3 is named in the same sentence as 102 diseases in open-access papers, as found by Europe PMC text mining. Sharing a sentence is not in itself a finding about the gene and the disease. The quoted sentences say what the papers report.
breast carcinoma (24 papers, 2007 to 2025). "Both Sp1 and Sp3 were associated with HDAC activity in human breast cancer cells." (PMID 37764768, 2023). "Moreover, the repressive functions of Sp3 transcription factors have recently been implicated in breast cancer cell lines." (PMID 17511886, 2007). "In human mammary carcinoma cells, SP3 binds to GC1 and GC2 elements of the topoisomerase IIα promoter, forming a DNA loop that can function either as a transcriptional activator or repressor." (PMID 37590265, 2023). "In breast cancer, penfluridol was reported to induce ROS-mediated cell growth inhibition and apoptosis via significantly downregulating specificity protein (Sp) 1, Sp3, and Sp424." (PMID 31308361, 2019). "A previous study showed that TSPO expression is regulated by the binding of Sp1, Sp3 and/or Sp4 to the proximal promoter region in human breast cancer cell lines, and a similar sequence was observed in the mouse Tspo gene." (PMID 31536603, 2019). "Here, we show that miR-506 inhibits migration and invasion of breast cancer cell lines through the SP3/DNMT1/MEG3 axis." (PMID 30386180, 2018). "The major finding of the present study is that miR-506 inhibits migration and invasion of breast cancer cell lines through an undescribed pathway SP1/SP3/DNMT1/MEG3." (PMID 30386180, 2018). "Next, we employed RT-qPCR and Western blot to detect mRNA and protein level of SP3 in normal and breast cancer cell lines, respectively." (PMID 30386180, 2018). "Since SP3 is a downstream target of miR-506 and promotes migration and invasion of breast cancer cells, we sought to ask if miR-506 regulates migration and invasion of breast cancer cell lines in an SP3-dependent manner." (PMID 30386180, 2018). "In agreement with results in tissues, expression levels of SP3 were higher in breast cancer cells (MDA-MB-231, MCF-7 and SKBR3) compared to MCF10A." (PMID 30386180, 2018). "Expectedly, SP3 depletion suppressed invasion of the two breast cancer cells (the invaded cell number was decreased by ~ 50% in SP3-silenced cells)." (PMID 30386180, 2018). "We revealed a novel epigenetic mechanism of how miR-506 and SP3 play a role in breast cancer progression." (PMID 30386180, 2018). "In parallel, the RT-qPCR assay revealed that expression levels of SP1 and SP3 were declined in miR-506 overexpressed breast cancer cells relative to that in NC mimic cells." (PMID 30386180, 2018). "The relevance of Sp1 and Sp3 in estradiol regulation of VEGF in breast cancer was demonstrated by binding assays in vitro (by EMSA) and in vivo (by ChIP)." (PMID 28394264, 2017). "The in vivo interactions of Sp1 and Sp3 with the GC elements of the topoisomerase IIα promoter were studied in doxorubicin-treated breast cancer cell lines using chromatin immunoprecipitation assays." (PMID 17511886, 2007). "Sp1/Sp3 co-transfection results, coupled with the results of Sp3 ChIP assays therefore suggest that Sp3 plays a critical role in the down-regulation of topoisomerase IIα in drug treated breast cancer cells." (PMID 17511886, 2007). "We investigated endogenous levels of Sp1, Sp3 and topoisomerase IIα as well as binding of both Sp1 and Sp3 to the GC boxes of the topoisomerase IIα promoter in breast cancer cell lines in vivo after short term doxorubicin exposure." (PMID 17511886, 2007). "SP3 silencing inhibits Akt signaling and breast cancer cell migration and invasion." (PMID 39545637, 2024). "To explore the mechanism underlying SP3 knockdown-attenuated metastasis of MCF-7 and MDA-MB-231 cells, we attempted to confirm whether SP3 also impacted the expression of DNMT1 in breast cancer cells." (PMID 30386180, 2018). "We firstly attempted to examine the effect of SP3 on metastasis of breast cancer." (PMID 30386180, 2018). "Similarly, VEGF regulation by estrogen in endometrial and breast cancer cells involves interactions of ER-α and Sp1 (or Sp3) with GC boxes in the core promoter region of VEGF." (PMID 28394264, 2017).
breast carcinoma (continued). "In breast cancer, Sp3 accelerates tumor cell growth by acting as a repressor of TGF signaling." (PMID 23326307, 2013). "For example, elevated Sp3 levels have been shown to promote pancreatic and breast cancer cell growth by inhibiting transcription of growth inhibitory genes including thosse encoding the cyclin-dependent kinase inhibitor p27 and the type II receptor for transforming growth factor-β." (PMID 18377656, 2008). "Notably, Sp3 has been involved in pancreatic cancer cells by its ability to suppress p27 expression through interaction with GC-rich promoter elements and in breast cancer by its role in accelerating tumor cell growth acting as a repressor of TGFB." (PMID 31533233, 2019). "With lower levels of topoisomerase IIα evident in drug treated breast cancer cells, these data suggest that Sp3 may play a vital role in the development of resistance to chemotherapy and supports earlier work that suggested Sp3 was upregulated in etoposide/teniposide-resistant KB cell lines." (PMID 17511886, 2007). "In this study, we collected breast cancer cells at 1st, 2nd, 3rd, and 4th which were numbered SP1, SP2, SP3 and SP4 in the spheroid formation experiment." (PMID 38037058, 2023). "It has been proven that butyrate-treated cells increase Sp1 and Sp3 occupation at the ATP2A3 promoter and increase ATP2A3 mRNA expression in gastric and breast cancer cell lines." (PMID 35893896, 2022). "Although SP1 and SP3 has been investigated in breast cancer, the detailed mechanism by which SP1 and SP3 regulate progression of breast cancer requires to be further investigated." (PMID 30386180, 2018). "Compared to SP3, SP1 has been extensively studied in breast cancer, thyroid cancer, hepatocellular cancer, pancreatic cancer, colorectal cancer, gastric cancer and lung cancer." (PMID 30386180, 2018). "For breast cancer, of the six predicted candidates (PRKCQ, ARAF, MAPK14, BRMS1, CDC42BPA, SP3), three (PRKCQ, ARAF, MAPK14) are members of at least one KEGG cancer relevant pathway." (PMID 25961669, 2015). "In ZR-75 breast cancer cells, estrogen regulation of VEGF expression is thought to act through ER- α/Sp1 and ER- α/Sp3 interactions with GC-rich motifs." (PMID 23369005, 2013). "Our data reveal a novel axis of miR-506/SP3/SP1/DNMT1/MEG3 in regulating migration and invasion of breast cancer cell lines, which provide rationales for developing effective therapies to treating metastatic breast cancers." (PMID 30386180, 2018). "Next, we performed wound healing assay to evaluate migration ability of human breast cancer cells with or without SP3." (PMID 30386180, 2018). "Moreover, treatment of penfluridol with A549 cells did not inhibit or slightly enhanced the expression of Sp1, Sp3, and Sp4, suggesting the underlying mechanisms involved in the anticancer action of penfluridol in NSCLC and breast cancer are different." (PMID 31308361, 2019). "In addition, we show an increased dysregulation of transduction signaling pathways, during different growth phases of SP3 vs. NSP2 development, suggesting targeting specific DEGs during different growth periods may lend to better carcinogenic therapeutic strategies in mammary tumors." (PMID 31040905, 2019).
colon carcinoma (17 papers, 2009 to 2025). "Mechanistic studies suggest that sulindac sulfide induces reactive oxygen species (ROS) which in turn downregulates expression of Sp1, Sp3 and Sp4 in colon cancer cells." (PMID 26673922, 2015). "We further assessed the involvement of the pro-oncogenic specificity protein (Sp) transcription factors Sp1, Sp3, and Sp4 in the antileukemic effect of high AA because high AA exhibits anticancer activity towards colon cancer cells." (PMID 23626851, 2013). "Further, the expression of Sp1, Sp3, and Sp4 was also downregulated by high AA in K562 cells, as was observed in colon cancer cells." (PMID 23626851, 2013). "We further assessed the involvement of Sp1, Sp3, and Sp4 in the antileukemic effect of high AA because high AA exhibits anticancer activity towards colon cancer cells, which is due in part to downregulation of Sp transcription factors and Sp-regulated genes." (PMID 23626851, 2013). "Colon cancer cell growth inhibition was accompanied by downregulation of Sp1, Sp3 and Sp4 proteins and decreased expression of Sp-regulated gene products including bcl-2, survivin, VEGF, VEGFR1, cyclin D1, c-MET and p65 (NFκB)." (PMID 23110215, 2012). "Results of this study has identified a novel pathway for aspirin-induced effects on Sp1, Sp3 and Sp4 in colon cancer cells, and current studies are focused on specific enzymes and pathways associated with the effects of aspirin on zinc homeostasis." (PMID 23110215, 2012). "Since NFκB (p65) and the β-catenin promoters contain GC-rich Sp binding sites, we used RNAi to determine the role of Sp1, Sp3 and Sp4 in regulation of p65, p50 and β-catenin in colon cancer cells." (PMID 23110215, 2012). "In colon cancer, HDAC inhibitors can induce cancer cell apoptosis by activating Krüppel-like factor 4, and Sp1/Sp3 can increase the apoptotic sensitivity of colon cancers to histone deacetylase inhibitors." (PMID 23148884, 2012). "In summary, we have shown that the anticancer activity of BA in colon cancer cells is due, in part, to downregulation of Sp1, Sp3, Sp4 and Sp-regulated prooncogenic gene products." (PMID 21864401, 2011). "Previous studies show that BA induces proteasome-dependent degradation of specificity protein (Sp) transcription factors Sp1, Sp3 and Sp4 in prostate cancer cells and this study focused on the mechanism of action of BA in colon cancer cells." (PMID 21864401, 2011). "The role of Sp3 in apoptosis regulation was analysed in Chinese hamster lung fibroblasts (R443) and colon carcinoma cells (LS174) conditionally expressing full-length Myc-tagged Sp3." (PMID 19212434, 2009). "This study demonstrates that sulindac sulfide, the active metabolite of sulindac which is known to exhibit anti-neoplastic activity in human and experimental models of colon cancer, also downregulates Sp1, Sp3, Sp4 and pro-oncogenic Sp-regulated genes in colon cancer cells." (PMID 26673922, 2015). "Colon cancer patients on low dose aspirin therapy (75 mg/d; ca. 1 mg/kg/d) would exhibit maximum average serum concentrations of salicylate (6.8 mM) and aspirin (0.21 mM) sufficient to inhibit colon cancer cell growth and decrease expression of Sp1, Sp3, Sp4 and Sp-regulated genes." (PMID 23110215, 2012). "In summary, this study demonstrates that aspirin induces caspase-dependent proteolysis of Sp1, Sp3 and Sp4 proteins in colon cancer cells and tumors and, this was accompanied by downregulation of several Sp-regulated genes involved in cell proliferation, survival and angiogenesis." (PMID 23110215, 2012). "Thus, pharmacologic doses of aspirin that give low mM serum concentrations can be accompanied by >30-fold higher concentrations of salicylate which are more than sufficient to inhibit colon cancer cell growth and decrease Sp1, Sp3, Sp4 and Sp-regulated genes." (PMID 23110215, 2012).
colon carcinoma (continued). "Sp1 and also Sp3 and Sp4 are highly expressed in cancer cells and in this study, we have used results of RNA interference (RNAi) to show that the three TFs individually play a role in the growth, survival and migration/invasion of breast, kidney, pancreatic, lung and colon cancer cell lines." (PMID 26967243, 2016). "Since overexpression of ZBTB10 and antisense-miR-27a also decreases expression of Sp1, Sp3, Sp4 and Sp-regulated genes in colon cancer cells, the mechanism of action of BA in RKO cells is linked to disruption of miR-27a:ZBTB10 as previously reported for CDODA-Me and GT-094 in colon cancer cells." (PMID 21864401, 2011). "Moreover, in HT-29 colon cancer cells, quercetin–resveratrol combination treatment reduced the proteins SP1, SP3, and SP4, transcription factors known to be overexpressed in colon cancer." (PMID 37373289, 2023). "Moreover, in HT-29 colon cancer cells, treatment with quercetin in combination with resveratrol resulted in decreased SP1, SP3 and SP4 proteins, transcription factors known to be overexpressed in colon cancer." (PMID 27681738, 2016). "Moreover, knockdown of Sp1, Sp3 and Sp4 (in combination) in RKO colon cancer cells also decreased expression of EGFR, cyclin D1, p65 and PTTG-1, confirming the role of Sp transcription factors in regulating expression of these genes." (PMID 21864401, 2011). "Moreover combined knockdown of Sp1, Sp3 and Sp4 using an oligonucleotide cocktail (iSp) also decreased expression of p65, PTTG-1, EGFR and cyclin D1 in RKO cells confirming their regulation by Sp transcription factors in colon cancer cells." (PMID 21864401, 2011).
pancreatic cancer (15 papers, 2008 to 2025). "We observed high expression of Sp1, Sp3 and Sp4 in pancreatic tumors from these mice, whereas low expression of these proteins has been reported in normal mouse tissues." (PMID 29389953, 2018). "We also observed that tumor growth in mice bearing L3.6pL pancreatic cancer cells depleted of Sp1 or Sp1, Sp3 and Sp4 (combined) was significantly lower than observed in studies using wild-type cells expressing these TFs." (PMID 26967243, 2016). "Tolfenamic acid induces proteasome-dependent downregulation of Sp1, Sp3 and Sp4 in pancreatic cancer cells." (PMID 26673922, 2015). "Metformin was reported to decrease SP1/SP3 expression and their downstream targets, such as Bcl-2, survivin, and cyclin D1, in pancreatic cancer cells." (PMID 26294325, 2015). "The antidiabetic drug metformin decreases expression of Sp1, Sp3, Sp4 and Sp-regulated genes in pancreatic cancer cells and metformin (0–20 mM) inhibited growth of HepG2, SNU-449 and SK-Hep-1 cells after treatment for 24 and 48 hr." (PMID 26317792, 2015). "Metformin is an antidiabetic drug that protects patients against pancreatic cancer and metformin downregulates Sp1, Sp3, Sp4 and pro-oncogenic Sp-regulated genes in pancreatic cancer cells and tumors." (PMID 26317792, 2015). "Sp3 enhances the growth of pancreatic cancer cells by suppressing p27 expression through interaction with GC-rich promoter elements." (PMID 23326307, 2013). "In bladder cancer cells, curcumin induced proteasome-dependent downregulation of Sp1, Sp3 and Sp4, whereas in pancreatic cancer cells this response was ROS-dependent and reversed by cotreatment with antioxidants such as GSH." (PMID 23194063, 2012). "Curcumin inhibits growth of several cancer cell lines, and studies in this laboratory in bladder and pancreatic cancer cells show that curcumin downregulates specificity protein (Sp) transcription factors Sp1, Sp3 and Sp4 and pro-oncogenic Sp-regulated genes." (PMID 23194063, 2012). "For instance, curcumin inhibited the proliferation of Panc28 and L3.6pL pancreatic cancer cells in vitro by down-regulating NF-kB-dependent gene transactivation and Sp1, Sp2 and Sp3 transcription factors, which are overexpressed in pancreatic cancers." (PMID 21859497, 2011). "This was consistent with studies in this laboratory showing that CDDO-Me induced ROS and ROS-dependent downregulation of Sp1, Sp3 and Sp4 and pro-oncogenic Sp-regulated genes and has been observed with other ROS-inducing anticancer agents in pancreatic cancer cells." (PMID 29389953, 2018). "Moreover, tumor growth in athymic nude mice bearing L3.6pL pancreatic cancer cells as xenografts were significantly decreased in cells depleted for Sp1, Sp3 and Sp4 (combined) or Sp1 alone." (PMID 26967243, 2016). "Studies in this laboratory have shown that curcumin inhibits bladder and pancreatic cancer cell and tumor growth and that the anticancer activity is due, in part, to downregulation of specificity protein (Sp) transcription factors Sp1, Sp3, Sp4 and Sp-regulated genes." (PMID 23194063, 2012). "The transcription factors Sp1, Sp3 and Sp4 are overexpressed in pancreatic cancer cells and like MALAT-1, knockdown of Sp1, Sp3 and Sp4 or Sp1/Sp3/Sp4 (combined) results in decreased cell growth, induces apoptosis, and decreases migration." (PMID 29389953, 2018). "By relieving the negative regulation of RREB1 on the ARHGEF2 promoter, we determined that ETS1 and SP3 are essential for the normal expression of ARHGEF2 and contribute to the migratory behavior of pancreatic cancer cells." (PMID 27835861, 2017). "Sp transcription factors Sp1, Sp3 and Sp4 are highly expressed in cancer cells/tumors and Sp1 is a negative prognostic factor for survival of gastric and pancreatic cancer and glioma patients." (PMID 26673922, 2015).